ARID1A (AT-rich interaction domain 1A)
Diseases named in the same sentence as ARID1A in open-access papers (continued):
Sharing a sentence is not in itself a finding about the gene and the disease.
mismatch repair deficiency (3 papers, 2022 to 2024). "A number of synthetically lethal therapeutic opportunities arise on the basis of ARID1A mutations and mismatch repair deficiency, utilizing inhibitors of PARP1, HDAC2/6, Aurora kinase A, CKD4/6, or PI3K/Akt." (PMID 36078038, 2022).
nasopharyngeal carcinoma (3 papers, 2020 to 2024). A carcinoma arising from the nasopharyngeal epithelium. "ARID1A was also found to play a tumor suppressor role in nasopharyngeal carcinoma (NPC), and deletion of ARID1A activated the AKT signaling pathway to promote tumor cell migration and invasion." (PMID 39697230, 2024).
neuroendocrine carcinoma (3 papers, 2022 to 2024). A malignant neuroendocrine neoplasm composed of cells containing secretory granules that stain positive for NSE and chromogranin. "Mutations in CDKN2A or RB1 co-occurring with SMARCA4 or ARID1A have been reported previously in olfactory neuroblastoma and neuroendocrine carcinoma." (PMID 38201285, 2023).
osteosarcoma (3 papers, 2023 to 2025). A usually aggressive malignant bone-forming mesenchymal neoplasm, predominantly affecting adolescents and young adults. "Transcriptional analysis in one study found that in mouse osteosarcoma models, genomic instability was the highest-rated hallmark in Arid1a knockout in mice compared to wild type." (PMID 40429787, 2025). "Upon histological evaluation of the resected tumors from mice with homozygous and heterozygous loss of Arid1a, there was classical evidence of osteosarcoma with the presence of an osteoid matrix." (PMID 39123453, 2024). "To investigate the impact of Arid1a loss on the osteosarcoma transcriptome, we conducted RNA-sequencing on 16 tumors derived from the mouse models, consisting of eight Arid1afl/fl knockout (KO) and eight wildtype (WT) samples." (PMID 39123453, 2024). "Genetic screening in this study discovered that the loss of the Arid1a gene is a crucial factor in the development and progression of osteosarcoma." (PMID 39123453, 2024). "WES performed on 21 patients with osteosarcoma identified ARID1A mutations in 43% of cases, but its biological role in OS is not clear." (PMID 37373240, 2023). "Mutations that result in loss of ARID1A have been shown to contribute to faster tumorigenesis, progression towards metastasis, and development of chemoresistance across several cancers including ovarian, colon, osteosarcoma, and esophageal cancer." (PMID 40429787, 2025). "Hence, more needs to be studied not only on the mutational status of Arid1a in osteosarcoma, but also the epigenetic mechanisms that regulate gene and protein expression." (PMID 39123453, 2024). "By utilizing our model, we can contribute to the understanding of the specific molecular events and pathways involved in chemoresistance and metastasis in osteosarcoma, particularly focusing on the potential for simultaneous targeting of DNA damage repair proteins in Arid1a-mutated osteosarcoma." (PMID 39123453, 2024). "Our findings suggest that Arid1a plays a role in genomic instability in aggressive osteosarcoma and a better understanding of this correlation can help with clinical prognoses and personalized patient care." (PMID 39123453, 2024). "This study establishes that Arid1a indeed plays a tumor suppressor role in aggressive osteosarcoma and opens an exciting new avenue for further studies into the molecular mechanisms underlying its effects." (PMID 39123453, 2024). "Unbiased pathway analyses suggest that Arid1a may contribute to the aggressiveness of osteosarcoma by dysregulating genomic instability." (PMID 39123453, 2024).
rectal cancer (3 papers, 2018 to 2022). A primary or metastatic malignant neoplasm that affects the rectum. "ARID1A is the third most significantly mutated gene in human rectal cancer, with a frequency of 39% in MSI type cancers." (PMID 29681787, 2018). "Since mutations in ARID1A have been shown to lead to the loss of protein expression in tumors, we next examined the frequency of the loss of ARID1A protein expression by immunohistochemical analysis of tissue microarrays from treatment naïve rectal cancer patients." (PMID 31217031, 2019).
soft tissue sarcoma (3 papers, 2022 to 2023). A malignant neoplasm arising from muscle tissue, adipose tissue, blood vessels, fibrous tissue, or other supportive tissues excluding the bones. "However, soft tissue sarcoma also harbors more mutations in chromatin modeler genes (e.g., ARID1A and KMT2D) and the neurotrophic tyrosine kinase receptor gene NTR1, as well as higher panel-specific TMB, compared to histiocytic sarcoma." (PMID 37414794, 2023).
squamous cell lung carcinoma (3 papers, 2020 to 2023). A carcinoma arising from squamous bronchial epithelial cells. "The squamous cell lung carcinomas showed two cases with ARID1A loss of function variants (E1718* and G1848fs), one FGFR3 S249C variant, one MAP2K1 P124L, and one case with PIK3CA amplification and E545A variant." (PMID 36125633, 2023).
synovial sarcoma (3 papers, 2022 to 2026). "Disruption of Arid1a or Arid1b (both CBAF-specific) retains synovial sarcoma character, while Smarcb1 (PBAF- and CBAF-specific) or Pbrm1 (PBAF-specific) disruption does not, although all accelerate SS18::SSX-driven tumorigenesis in mice." (PMID 41423472, 2025). "The most common molecular alterations (excluding canonical SS18::SSX fusions in synovial sarcoma) involved ATM (18%), ARID1A (9%), CTNNB1 (9%), PALB2 (9%), and NF1 (9%), while 46% of profiled cases showed no detectable alterations." (PMID 41504936, 2026).
angiosarcoma (2 papers, 2023 to 2025). A malignant tumor arising from the endothelial cells of the blood vessels.
Anxiety (2 papers, 2022 to 2025). Intense feelings of nervousness, tension, or panic often arise in response to interpersonal stresses. "Our findings that deficient neurogenesis and anxiety‐like behaviours following microglial Arid1a deletion was rescued by Il4 stimulation in vivo opened a new avenue of mitigating depressive illness through manipulation of microglial polarization states." (PMID 35854653, 2022). "Increased chromatin accessibility upon Arid1a ablation resulted in enhanced M1 microglial polarization and weakened M2 polarization, which led to abnormal neurogenesis and anxiety‐like behaviours." (PMID 35854653, 2022). "Collectively, these results suggested that deletion of microglial Arid1a did not cause autism‐like behaviour or learning and memory deficits, but resulted in anxiety‐like behaviour." (PMID 35854653, 2022). "Importantly, microglial polarization anomaly induced by absence of Arid1a led to abnormal neurogenesis and anxiety‐like behaviour." (PMID 35854653, 2022).
bladder (2 papers, 2018 to 2025). "Importantly, ARID1A significantly co-occurred with PTEN alterations, consistent with functional interaction between the two genes in driving prostate tumorigenesis highlighted by our Sleeping Beauty screen." (PMID 39885328, 2025).
brain tumors (2 papers, 2018 to 2019). "Genetic defects in ARID1A, ARID1B, and CHEK2 have been reported in brain tumors." (PMID 29610389, 2018).
clear cell ovarian tumor (2 papers, 2021). "AT-rich interactive domain-containing 1A (ARID1A) gene mutations are known to occur in gastric, endometrial, and clear cell ovarian tumors." (PMID 33608032, 2021). "AT-rich interactive domain-containing 1A (ARID1A) gene mutations are present in gastric, endometrial, and clear cell ovarian tumors." (PMID 33608032, 2021). "It was also observed that HDAC inhibition significantly suppressed the tumor growth in an ARID1A−/−/PIK3CAMUT genetic clear cell ovarian tumor mouse model and this similar molecular condition of ARID1A deletion and PIK3CA mutation is present in the IU-TAB-1 cell line." (PMID 34136086, 2021).
cyst (2 papers, 2015 to 2025). A sac-like closed membranous structure that may be empty or contain fluid or amorphous material. "Among 47 ovarian endometriotic cysts with carcinoma, ARID1A loss was present in 31 (66%) cases that involved both the carcinoma and nearby cyst epithelium but not the distant cyst epithelium." (PMID 40364006, 2025).
esophageal squamous cell carcinoma (2 papers, 2016 to 2024). Esophageal squamous cell carcinoma (ESCC) is a type of esophageal carcinoma (EC) that can affect any part of the esophagus, but is usually located in the upper or middle third. "As for esophageal squamous cell carcinomas (ESCCs), somatic mutations have been detected for ARID1A, ARID2, and PBRM1 by exome-sequencing." (PMID 26812616, 2016).
fallopian tube cancer (2 papers, 2018 to 2022). A primary or metastatic malignant neoplasm that affects the fallopian tube.
Fanconi anemia (2 papers, 2021 to 2025). Fanconi anemia (FA) is a hereditary DNA repair disorder characterized by progressive pancytopenia with bone marrow failure, variable congenital malformations and predisposition to develop hematological or solid tumors. "Most detected variants affected the Fanconi anemia/DNA repair pathway (34%, ATM, FANCA, FANCI, MLH1, MSH6, POLE, RAD51C, RAD51D) followed by mutations altering the SWI/SNF (SWItch/sucrose non-fermentable) complex (22%, ARID1A and SMARCA4)." (PMID 34200508, 2021). "Some of these non-core genes include ARID1A, ATM, RAD51, CHEK2, and the Fanconi anemia genes." (PMID 39860372, 2025).
gallbladder cancer (2 papers, 2022 to 2025). "In gallbladder cancer, ARID1A expression negatively correlated with prognosis and was identified as an independent factor for overall survival." (PMID 40429787, 2025). "High PD-L1 expression due to the downregulation of the ARID1A gene is also seen in gallbladder cancer, where CD8+ T cells are inactivated as a result." (PMID 40429787, 2025). "Recent studies have confirmed that AT-rich interactive domain-containing protein 1A (ARID1A) plays a critical role in tumorigenesis, but its role in gallbladder cancer (GBC) remains unclear." (PMID 35198440, 2022).
germ cell tumor (2 papers, 2021 to 2025). A benign or malignant, gonadal or extragonadal neoplasm that originates from germ cells. "Similar to our findings, ARID1A downregulation in testicular germ cell tumors also leads to ATF3 upregulation." (PMID 34941867, 2021).
goblet cell adenocarcinomas (2 papers, 2023). "Both SMARCA4 and ARID1A are mutated in appendiceal goblet cell carcinoids, mixed goblet cell carcinoid–adenocarcinomas, and some appendiceal mucinous adenocarcinomas and adenocarcinomas." (PMID 37566041, 2023). "Most of these mutations were also identified in other studies; for example, mutations in KDM6A, KMT2D, SMARCA4, and ARID1A have been previously reported not only in appendiceal adenocarcinomas but also in appendiceal goblet cell carcinomas." (PMID 37566041, 2023).
Hepatic steatosis (2 papers, 2024 to 2025). Steatosis is a term used to denote lipid accumulation within hepatocytes. "Deletion of ARID1A in liver has been shown to increase susceptibility to the development of hepatic steatosis and insulin resistance by impairing FA oxidation." (PMID 40231468, 2025).
histiocytic sarcoma (2 papers, 2023). An aggressive malignant neoplasm with a poor response to therapy, usually presenting as stage III/IV disease. "These include ARID1B, ARID2, BCL11B, and SMARCA2 mutations in post-transplant lymphoproliferative disorders, ARID1A mutations in primary histiocytic sarcoma, and ARID1A mutations in aggressive Langerhans cell histiocytosis." (PMID 36810086, 2023).
hyperplasia (2 papers, 2021 to 2025). An abnormal increase in the number of cells in an organ or a tissue with consequent enlargement. "A literature review summarized these findings and indicated that high risk of cancer development was attributable to elevated estrogen concentrations leading to cystic malignant hyperplasia and/or ARID1A gene (SWI/SNF family member) mutations and, consequently, loss of BAF250a expression." (PMID 34458137, 2021).
Insulin resistance (2 papers, 2022 to 2025). Increased resistance towards insulin, that is, diminished effectiveness of insulin in reducing blood glucose levels. "Other data have demonstrated that the loss of Arid1a enhances NAFLD by downregulating PPARα, thereby blocking fatty acid oxidation and leading to lipogenesis and insulin resistance." (PMID 36432495, 2022).
intellectual disability syndromes (2 papers, 2021 to 2025). "However, the high sequence similarity between ARID1B and ARID1A and the association of ARID1B loss with intellectual disability syndromes pose challenges for the development of small‐molecule inhibitors that are selectively ARID1B‐specific and can be precisely delivered to affected tissues." (PMID 40671262, 2025).
invasive carcinoma (2 papers, 2016 to 2019). A carcinoma that is not confined to the epithelium, and has spread to the surrounding stroma.
ischemic heart disease (2 papers, 2023 to 2024). "In ischemic heart disease, Arid1a expression is enhanced in cardiomyocytes of the border zone region." (PMID 37543677, 2023). "ARID1A plays a role in ischemic heart disease by suppressing cardiac proliferation." (PMID 39436707, 2024).
kidney cancer (2 papers, 2017 to 2023). Primary or metastatic malignant neoplasm involving the kidney. "However, molecular mechanisms of ARID1A deficiency to induce angiogenesis in kidney cancer remain underinvestigated." (PMID 38017409, 2023). "However, molecular mechanisms of ARID1A deficiency to regulate angiogenesis in kidney cancer remain underinvestigated." (PMID 38017409, 2023).
liver disease (2 papers, 2021 to 2024). "Other relatively strong positive associations are found between liver disease etiology and genes IDH1 and ARID1A (phi = 0.82 and phi = 0.77 for HCV and HIV infection, respectively), and a moderate association was also observed between HBV infection and GNAS (phi = 0.68)." (PMID 34885159, 2021).
lung carcinoid (2 papers, 2023 to 2025). "The absence of the ARID1A variant in the diagnostic lung biopsy suggests that it most likely drove later tumor progression and was not an initiating driver variant, despite being identified as a driver in other cancer types and being recurrently detected in previous lung carcinoid studies." (PMID 36968225, 2023).
medulloblastoma (2 papers, 2021 to 2022). A malignant, invasive embryonal neoplasm arising from the cerebellum. "The oncogenic effect of mutations in the fusion genes such as ARID1A, PVT1, GFI1, MYCN, DNMT1, and TET3 has been identified in various tumors including medulloblastomas to regulate tumorigenesis, suggesting that the predicted inframe fusion proteins may possess oncogenic potential." (PMID 33681213, 2021).
metastasis (2 papers, 2021 to 2023). The spread or migration of cancer cells from one part of the body (where they first appeared) to another. "Clinically, the loss of ARID1A expression was correlated with larger tumor size, deeper invasion, lymph node metastasis, and a poor prognosis." (PMID 34572812, 2021).
metastatic colorectal cancer (2 papers, 2015 to 2020). "A patient with metastatic colorectal cancer harboring molecular aberrations, including ATM loss and an ARID1A mutation, achieved RECISTv1.1 complete response and maintained this response, with a progression-free survival of 29 months at last assessment." (PMID 32568634, 2020).
metastatic melanoma (2 papers, 2021 to 2022). A melanoma that has spread from its primary site to another anatomic site. "Ideally prospectively collected larger datasets should be analyzed to further assess the ideal therapeutic regimen and possible further implications of ARID1A mutations on metastatic melanoma." (PMID 35565222, 2022).
myelodysplastic syndrome (2 papers, 2022 to 2023). A clonal hematopoietic disorder characterized by dysplasia and ineffective hematopoiesis in one or more of the hematopoietic cell lines. "Moreover, sequencing studies carried out on AML and/or myelodysplastic syndromes (MDS) have found recurrent deleterious mutations in SWI/SNF genes including ARID2, ARID1A and ARID1B, SMARCA2, and SMARCA4." (PMID 36941700, 2023).
myeloma (2 papers, 2022 to 2025). "Our mutation profile (ARID1A, KMT2D, BCL7A, PTPN11, NUP214) and high CNV load converge with patterns reported across extramedullary/myeloma cohorts, notably MAPK pathway lesions and 1q amplifications." (PMID 41378284, 2025).
myopia (2 papers, 2024 to 2025). "Analysis of protein interactions in the STRING online database revealed that the ARID1A protein interacts with the high myopia gene-related proteins FGFR3, ASXL1, ERBB3, and SOX4, whereas the ARID1A protein antagonizes the ARID1B protein." (PMID 38790056, 2024).
neuroendocrine neoplasm (2 papers, 2020). Endocrine tumors, also referred to as neuroendocrine tumors (NETs), are defined by a common phenotype which is characterized by the expression of general markers (neuron specific enolase, chromogranin, synaptophysin) and hormone secretion products. "Similar to the neuroendocrine tumors (NETs) of other sites, NEBCs also host mutations in chromatin remodeling genes including ARID1A and ATRX." (PMID 32414120, 2020).